HIBADH (3-hydroxyisobutyrate dehydrogenase)
Synonyms: NS5ATP1
Tractability: Small molecule: a structure with a bound ligand is known; it has a high-quality binding pocket. PROTAC: ubiquitination databases record sites on it; its protein half-life has been measured.
Target class: Enzyme; Oxidoreductase
Gene: Protein-coding gene on chromosome 7 (27,525,440 to 27,662,988, reverse strand). Ensembl gene ENSG00000106049.
Subcellular location: Mitochondrion
Pathways (Reactome):
Metabolism: Branched-chain amino acid catabolism
Gene Ontology:
Molecular function: 3-hydroxyisobutyrate dehydrogenase activity; protein binding; NAD binding; NADP binding; oxidoreductase activity
Biological process: L-valine catabolic process
Cellular component: mitochondrion; mitochondrial matrix
Genetic constraint (gnomAD): Loss-of-function variants: 21 observed, 26.81 expected, observed/expected ratio (o/e) 0.78, 90% interval 0.56 to 1.13. The upper end of that interval is the gene's LOEUF score, 1.13, which puts it in group 4 of 6, group 1 being the genes least tolerant of losing a copy. Missense variants: 374 observed, 373.12 expected, observed/expected ratio (o/e) 1, 90% interval 0.92 to 1.09. Synonymous variants: 143 observed, 134.6 expected, observed/expected ratio (o/e) 1.06, 90% interval 0.93 to 1.22.
Gene-disease validity (ClinGen):
ClinGen rates the evidence that HIBADH causes each of these diseases.
3-hydroxyisobutyric aciduria (autosomal recessive): Limited. 3 hydroxyisobutyric aciduria is characterized by ketoacidotic episodes, cerebral anomalies and facial dysmorphism.
Homologues: Orthologues: chimpanzee HIBADH (100% identical), macaque HIBADH (99% identical), dog HIBADH (96% identical), rabbit HIBADH (96% identical), mouse Hibadh (90% identical), pig HIBADH (90% identical), rat Hibadh (90% identical), tropical clawed frog hibadh (81% identical), guinea pig HIBADH (74% identical), zebrafish hibadhb (74% identical), Caenorhabditis elegans B0250.5 (48% identical), Drosophila melanogaster CG15093 (44% identical). Paralogues in human: GLYR1 (26% identical).
Diseases named in the same sentence as HIBADH in open-access papers:
HIBADH is named in the same sentence as 16 diseases in open-access papers, as found by Europe PMC text mining. Sharing a sentence is not in itself a finding about the gene and the disease. The quoted sentences say what the papers report.
nephrolithiasis (3 papers, 2022 to 2024). The presence of a calculus in the pelvis of the kidney; this is most often composed of mineral salts and proteins. "Notably, genes PPP2R3A for BUN, VAMP8 for UACR, DOCK7 for creatinine, and HIBADH for kidney stones were identified as shared risk genes by all three methods." (PMID 39086896, 2024). "Notably, rs17438465 is located between EVX1 and HIBADH, genes that have been associated with nephrolithiasis and cardiovascular disease." (PMID 37124606, 2023). "Among these, rs74637005 is located in the exonic region of NFU1, a gene previously shown to be associated with both calcium levels and elevation in metabolic biomarkers and rs17438465 is located between EVX1 and HIBADH, genes that have been associated with nephrolithiasis and cardiovascular disease." (PMID 37124606, 2023). "Our results elucidated the significance of genetic variation at WDR72, DGKH, CLDN14, SLC34A1, and HIBADH in Chinese patients with nephrolithiasis." (PMID 35910217, 2022). "Finally, HIBADH, previously connected to kidney stones, has been documented to be involved in valine metabolism disorders,a pathway recently implicated in sepsis." (PMID 39086896, 2024).
Obesity (2 papers, 2013 to 2021). Accumulation of substantial excess body fat. "As we found in the survival analyses, 5 DE mRNAs (SORCS1, FLRT3, HIBADH, CATSPER1, and MAP3K8) and 5 DE miRNAs (hsa-miR-3130-2, hsa-miR-148b, hsa-miR-2681, hsa-miR-4487, and hsa-miR-3613) of obesity-related ccRCC were found in VAT." (PMID 34621242, 2021).
type 2 diabetes (2 papers, 2021 to 2022). "HIBADH (3-hydroxyisobutyrate dehydrogenase) has been previously implicated in insulin resistance and risk of incident type 2 diabetes and gestational diabetes mellitus." (PMID 33777101, 2021). "HIBADH gene was identified as a candidate gene for type 2 diabetes mellitus." (PMID 35910217, 2022).
anxiety disorder (1 paper, 2018). A category of psychiatric disorders which are characterized by anxious feelings or fear often accompanied by physical symptoms associated with anxiety. "Further analysis showed the possible increased activity of alanine-glyoxylate transaminase and 3-hydroxyisobutyrate dehydrogenase and decreased activity of aldehyde oxidase in patients with depression and anxiety disorders." (PMID 30232320, 2018).
Calcium nephrolithiasis (1 paper, 2022). The presence of calcium-containing calculi (stones) in the kidneys. "Our results indicated that rs578595 at WDR72, rs1037271 at DGKH, rs12654812 at SLC34A1, rs12539707 at HIBADH, and rs12626330 at CLDN14 were associated with the risk of calcium nephrolithiasis in Chinese Han population." (PMID 35910217, 2022). "Moreover, rs12654812 at SLC34A1 (p = 0.0427, OR = 1.170), rs12539707 at HIBADH (p = 0.0179, OR = 0.734), rs1037271 at DGKH (p = 0.0096, OR = 0.828) and rs12626330 at CLDN14 (p = 0.0080, OR = 1.213) indicated suggestive associations with calcium nephrolithiasis." (PMID 35910217, 2022).
virus infection (1 paper, 2020). "The lower expression level of HIBADH in the A35 strain following BmNPV infection indicates its potential role in inhibiting virus infection." (PMID 32695093, 2020).
tumor (2 papers, 2019 to 2024). "Additionally, a significantly differential expression ofcircHIBADH, but not the parental genes (HIBADH), was found between normal and tumor tissues, suggesting that circRNA functions independently from mRNAs, which may be modulated by rs11973492." (PMID 38808547, 2024).
HIBADH also shares sentences with these, for which no sentence is quoted: acute kidney injury (1 paper); cancer (1); cardiovascular disease (1); depression (1); gestational diabetes mellitus (1); Insulin resistance (1); lung carcinoma (1); Sepsis (1); type 2 diabetes mellitus (1).